IL18 (interleukin 18)
Diseases named in the same sentence as IL18 in open-access papers (continued):
Sharing a sentence is not in itself a finding about the gene and the disease.
lymph node metastasis (4 papers, 2013 to 2023). "Patients with G/C alleles of IL-18 -137 correlated with a lower clinical stage, tumor size, and non-lymph node metastasis compared with patients with G/G alleles." (PMID 24349532, 2013). "However, patients with G/C alleles of IL-18 -137 were correlated with a lower clinical stage (AOR=0.59; 95% CI=0.39-0.89; p=0.01), smaller tumor size (AOR=0.56; 95% CI=0.35-0.87; p=0.01), and non-lymph node metastasis (AOR=0.51; 95% CI=0.32-0.80; p=0.003)." (PMID 24349532, 2013). "Patients with G/C alleles IL-18 -137G/C polymorphism showed a decreased risk of developing Stages III-IV (AOR=0.59; 95% CI=0.39-0.89; p=0.01), a tumor size > T2 (AOR=0.56; 95% CI=0.35-0.87; p=0.01), and lymph node metastasis (AOR=0.51; 95% CI=0.32-0.80; p=0.003)." (PMID 24349532, 2013). "The high levels of IL-18 and low levels of IL-37 in the serum and PBMC of OSCC facilitate the development of advanced tumor stage and lymph node metastasis (the odd ratios of IL-18/IL-37 is 4.903 and 12.613, respectively)." (PMID 34248996, 2021). "In OSCC patients with lymph node metastasis and a severe TNM stage, serum IL18 levels were significantly higher than those in patients without lymph node metastasis or a severe TNM stage." (PMID 38139000, 2023).
memory impairment (4 papers, 2019 to 2022). "It has been reported that MPEP restored LTP in the DG in pathological conditions through an attenuation of the effect of interleukin-18 (IL-18), a pro-inflammatory cytokine whose level is elevated in pathological states associated with learning and memory impairments." (PMID 30970677, 2019). "NLRC4 inflammasome, via IL-1β and IL-18, contributes to memory impairment and neuroinflammation in a rat model of Alzheimer-like disease." (PMID 33584697, 2020). "Scopolamine induced memory impairment and inflammation by activating various inflammatory mediators such as Aβ/NF-κB/TNF-α/COX-2/IL-18, and PGE2 along with oxidative stress." (PMID 36544525, 2022). "Interestingly, similar to IL-6 and IL-18, TNF-α is also a product of activated microglia and is known to enhance memory impairment in mouse models of AD." (PMID 35648273, 2022).
Miscarriage (4 papers, 2015 to 2024). A pregnancy that ends at a stage in which the fetus is incapable of surviving on its own, defined as the spontaneous loss of a fetus before the 22th week of pregnancy. "Three polymorphisms (rs360717, rs187238, rs1946518) in the promoter region of IL-18 gene were selected for genotyping, and then we analyzed the association between the three SNPs and the risk of idiopathic recurrent miscarriage." (PMID 25690033, 2015). "Association between three SNPs in the promoter region of IL-18 gene and risk for idiopathic recurrent miscarriage in Chinese Han population." (PMID 25690033, 2015). "Statistically significant higher concentrations of NLRP3 and IL-18 were found in the sera of all women with miscarriage as compared to the values obtained in the control group." (PMID 39408839, 2024). "In the placental tissue samples, a higher expression of IL-1β, IL-18, and Caspase-1 proteins was noted in women who had experienced miscarriage as compared to the control group." (PMID 39408839, 2024). "The concentrations of NLRP3, IL-1β, IL-18, and cytochrome C in the serum of patients after miscarriage were measured by means of the immunoenzymatic method." (PMID 39408839, 2024). "Significantly higher concentrations of NLRP3 and IL-18 were demonstrated in the serum of patients with miscarriage as compared to the control group." (PMID 39408839, 2024). "The assessment of placental tissue samples revealed a statistically significant higher expression of IL-1β (p < 0.0001), IL-18 (p < 0.0001), and Caspase-1 (p < 0.0001) proteins in all women with miscarriage as compared to the control group." (PMID 39408839, 2024). "We demonstrated the excessive activation of inflammasome NLRP3, IL-18, and IL-1β in spontaneous miscarriage compared to normal pregnancy." (PMID 35745744, 2022). "Particularly increased IL-18 levels appeared to be critical in early pregnancy and served as a point of differentiation between healthy pregnancies and those culminating in miscarriage." (PMID 27747236, 2016). "This hypothesis is supported by the high expression of IL-1β and IL-18, along with elevated levels of Caspase-1 in the placenta tissue of women who experienced miscarriage." (PMID 39408839, 2024). "In aggregate, attempts to manipulate the GPR124 and inflammasome NLRP3, IL-18, and IL-1β signaling that have a critical role in spontaneous miscarriage may be a way to clarify the actions of mi138-5p in decidual endometrial stromal cells related to embryo implantation and early pregnancy." (PMID 35745744, 2022). "Significantly higher median concentrations of IL-18 and IL-1β were observed in the sera of women with NET-negative miscarriages as compared to the control values." (PMID 39408839, 2024). "Expression of IL-18 was observed in 90% of women with miscarriage (45% strong and 45% weak), with no expression in the control group." (PMID 39408839, 2024). "In contrast, GRP124 with siRNA invalidated the GRP124-regulated expression of NLRP3, IL-18, and IL-1β in human decidual endometrial stromal cells, indicating that the effects of GRP124 on spontaneous miscarriage are through the expression of inflammasome NLRP3, IL-18, and IL-1β." (PMID 35745744, 2022).
mucositis (4 papers, 2015 to 2022). Mucositis is inflammation and damage of the mucous membranes lining the mouth and other parts of the gastrointestinal (GI) tract. "Mucositis causes cell damage, bacterial/endotoxin translocation and production of cytokines including IL–1 and IL–18." (PMID 26440613, 2015). "Three confounders were identified in the present study, as our data demonstrated that mucositis, weight loss, and smoking pack-years impacted levels of IL-6 and IL-10, whereas smoking pack-years had a strong influence on IL-18 serum levels, corroborating some earlier findings." (PMID 35682983, 2022). "Numerous studies have revealed elevated productions of the inflammasome-dependent cytokines IL-1β and IL-18 during clinical and experimental chemotherapy-induced mucositis." (PMID 34310611, 2021).
myelodysplastic syndrome (4 papers, 2020 to 2025). A clonal hematopoietic disorder characterized by dysplasia and ineffective hematopoiesis in one or more of the hematopoietic cell lines. "This study investigated the expression levels of NLRP6, IL-1β and IL-18 in patients with myelodysplastic syndrome (MD) and their potential diagnostic value." (PMID 40837366, 2025).
necrotizing enterocolitis (4 papers, 2008 to 2020). Necrotizing enterocolitis (NEC) is a devastating disease that affects mostly the intestine of premature infants. "Premature infants with reduced birth weight are atrisk of developing necrotizing enterocolitis and IL-18 that is also involved in the pathogenesisof this disease." (PMID 18949051, 2008). "Analysis of the association between disease severity andgenotype frequencies at the −607 position ofthe IL-18 gene showed that the AA genotype frequency is significantly higher inpatients with the third and most severe stage of necrotizing enterocolitis,when the intestinal wall is perforated." (PMID 18949051, 2008).
nephrotic syndrome (4 papers, 2013 to 2025). A collection of symptoms that include severe edema, proteinuria, and hypoalbuminemia; it is indicative of renal dysfunction. "Urinary excretion of interleukin-18 (IL-18)/CXCL8, MCP-1/CCL2, and RANTES/CCL5 was not different in an analysis of patients with steroid-resistant or steroid-sensitive nephrotic syndrome." (PMID 26989679, 2016).
Newcastle disease (4 papers, 2012 to 2025). A condition caused by infection by the Newcastle disease virus, which may be characterized by conjunctivitis, respiratory illness, and diarrhea. "On the other hand, the vaccine adjuvant IL-18 has been proven, for example, in a DNA vaccine against Newcastle disease." (PMID 38140192, 2023). "Higher HI titers induced in chickens immunized with the Newcastle disease vaccine co-administrated with chicken IL-18 further confirm the immunostimulatory activities of chicken IL-18 in vivo." (PMID 22866758, 2012). "IL18 is a potent adjuvant for Newcastle disease and infectious bursal disease vaccine, indicating that the carvacrol-induced upregulation of IL-18R may have the potential to improve in ovo vaccination for Marek’s disease." (PMID 39828746, 2025).
plague (4 papers, 2015 to 2021). Plague is a severe bacterial infection caused by the gram-negative bacterium Yersinia pestis. "The NLRP12 inflammasome was reported to play an important role in the recognition of Yersinia pestis, the causative agent of plague, through controlling interleukin-18 (IL-18) and IL-1β production." (PMID 29293680, 2018). "Yersinia pestis, the causative agent of plague, harbors a T3SS which is particularly effective in suppressing innate immunity and release of pro-inflammatory cytokines IL-1β and IL-18, potent triggers of anti-bacterial responses." (PMID 27911947, 2016). "The fact that so many of the Y. pestis T3SS components are participating in regulation of IL-1β/IL-18 release suggests that these effects are essential for maximal control of innate immunity during plague." (PMID 27911947, 2016).
pneumonitis (4 papers, 2015 to 2024). An inflammatory process affecting the lung parenchyma. "In contrast, IL-18 seems to be more related to pleuritis, pneumonitis, and serologic markers associated with liver injury such as AST, ALT, ferritin, and LDH." (PMID 33652679, 2021). "Moreover, drug-induced pneumonitis has been particularly implicated in the inflammasome-mediated IL-1β and IL-18 production." (PMID 33414419, 2021). "For instance, pneumonitis induced by bleomycin, a glycopeptide anticancer agent, is mitigated in IL-18 or caspase-1 knockout mice." (PMID 33414419, 2021).
polyarthritis (4 papers, 2006 to 2021). "The IL-6-dominant subset has a more severe polyarthritis and higher serum levels of matrix metalloproteinase, whereas the IL-18-dominant subset was more prone to develop MAS." (PMID 34041254, 2021). "In fact, IL-18-/- mice still develop polyarthritis and express pro-inflammatory cytokines in the context of Dnase2-deficiency." (PMID 26114879, 2015). "The IL-6-dominant subset had a more severe polyarthritis and higher serum levels of matrix metalloproteinase (MMP-3), whereas the IL-18-dominant subset was more prone to develop MAS." (PMID 27999545, 2016). "However, given the fact that IL-18 deficiency does not protect Dnase2-deficient animals from polyarthritis or pro-inflammatory gene expression, Aim2-dependent IL-18 production or maturation appears to be an epiphenomenon rather than a cause in this disease model." (PMID 26114879, 2015). "In the other JIA subgroups, mean IL-18 levels in patients with and without the S01/S01 diplotype configuration were 572 ± 327 pg/ml versus 325 ± 302 pg/ml in those with polyarthritis, and 252 ± 124 pg/ml versus 219 ± 48 pg/ml in those with oligoarthritis." (PMID 16563174, 2006).
prediabetes (4 papers, 2016 to 2024). "IL-18, IL-6, and TNF-α were selected as the focus of this study due to their strong association with the chronic inflammation underlying prediabetes and its progression to cardiovascular disease." (PMID 40027364, 2024). "Elevated levels of IL-18, NFATC4, TNF-α, and IL-6 were all associated with significantly higher odds of prediabetes compared to healthy controls (all P < 0.001)." (PMID 40027364, 2024). "It was found that higher levels of inflammatory markers (IL-18, TNF-α, IL-6) and increased NFATC4 gene expression were associated with a greater risk of prediabetes compared to healthy controls." (PMID 40027364, 2024). "Elevated IL-18, IL-6, and TNF-α levels were associated with significantly increased prediabetes odds in univariate analysis (all P < 0.001)." (PMID 40027364, 2024). "Receiver operating characteristic (ROC) curve analysis identified IL-18 and NFATC4 as the most promising biomarkers for predicting prediabetes, followed by TNF-α and IL-6." (PMID 40027364, 2024). "ROC curve analysis evaluated the predictive ability of four inflammatory markers-IL-18, TNF-α, IL-6, and NFATC4-for classifying prediabetes cases and controls." (PMID 40027364, 2024). "Multivariate regression analysis further identified socioeconomic status (SES), IL-18, NFATC4, TSH, triglycerides, and HDL as independent predictors of prediabetes." (PMID 40027364, 2024).
primary biliary cholangitis (4 papers, 2015 to 2025). Primary biliary cholangitis (PBC) is a chronic and slowly progressive cholestatic liver disease of autoimmune etiology characterized by injury of the intrahepatic bile ducts that may eventually lead to liver failure. "The level of Il-18 increases in various human diseases such as rheumatoid arthritis, primary biliary cirrhosis (PBC), autoimmune hepatitis, Crohn disease, lymphohistiocytosis, leukemia, encephalomyelitis and SLE patients." (PMID 27047807, 2016).
salmonellosis (4 papers, 2010 to 2024). Infections with bacteria of the genus salmonella. "In mice, IL-18-mediated NK cellular cytotoxicity through perforin responses is crucial for resistance against salmonellosis during the early stages of infection." (PMID 38918457, 2024). "IL-1β and IL-18 are primarily responsible for triggering the intestinal inflammatory response characteristic of salmonellosis." (PMID 35338975, 2022). "The serum IFNγ, IL-12 and IL-18 levels were increased significantly in patients with both systemic and gastrointestinal form of salmonellosis." (PMID 20161765, 2010).
triple-negative breast carcinoma (4 papers, 2017 to 2025). An invasive breast carcinoma which is negative for expression of estrogen receptor (ER), progesterone receptor (PR), and human epidermal growth factor receptor 2 (HER2). "IL-18 expression was higher in the triple negative breast cancer (TNBC) cells (MDA-MB-231 and HCC-70) compared to that in the other subtypes." (PMID 28415798, 2017). "Park's team speculated that IL18 contributes to the poor prognosis of triple-negative breast cancer patients by inducing immunosuppression through PD-1 expression on NK cells." (PMID 40838069, 2025). "Park’s team speculated that IL18 contributes to the poor prognosis of triple-negative breast cancer patients by inducing immunosuppression of PD-1 expression on NK cells." (PMID 36591509, 2022).
viral hepatitis (4 papers, 2019 to 2024). An acute or chronic inflammation of the liver parenchyma caused by viruses. "Of note, IL-18 has been associated with susceptibility and disease progression of other forms of viral hepatitis, including hepatitis B, hepatitis C, and hepatitis E." (PMID 34066709, 2021). "So we call on scholars to examine associations between polymorphisms in CTLA-4/IL-18 and viral hepatitis in other populations." (PMID 31801640, 2019). "The aim of this study was to more comprehensively analyse associations between genetic polymorphisms in CTLA-4/IL-18 and viral hepatitis by combing the results of all relevant association studies." (PMID 31801640, 2019). "Fourth, we aimed to investigate associations between all polymorphisms in CTLA-4/IL-18 and viral hepatitis in the very beginning." (PMID 31801640, 2019). "In the past 20 years, results about associations between polymorphisms in CTLA-4/IL-18 and viral hepatitis were already reported by many association studies, yet the conclusions of these studies were still inconsistent." (PMID 31801640, 2019). "Relationship of genetic polymorphisms in cytotoxic T-lymphocyte-associated antigen 4 (CTLA-4) and interleukin-18 (IL-18) with susceptibility to viral hepatitis was already investigated by many association studies." (PMID 31801640, 2019). "Firstly, the results regarding associations between polymorphisms in CTLA-4/IL-18 and viral hepatitis were based on combining unadjusted findings of eligible studies due to the lack of raw data." (PMID 31801640, 2019). "To better analyse associations between polymorphisms in CTLA-4/IL-18 and viral hepatitis, we carried out this study to get a more statistically reliable conclusion by combing the results of all relevant studies." (PMID 31801640, 2019). "Twenty-three articles were about IL-18 polymorphisms and viral hepatitis." (PMID 31801640, 2019). "Secondly, the relationship between polymorphisms in CTLA-4/IL-18 and viral hepatitis may also be affected by environmental factors." (PMID 31801640, 2019). "So these variations may influence biological function of CTLA-4/IL-18, result in immune dysfunction, impact anti-viral immune responses and ultimately confer susceptibility to viral hepatitis." (PMID 31801640, 2019). "Thus, our meta-analysis may be statistically insufficient to observe the real underlying associations between polymorphisms in CTLA-4/IL-18 and viral hepatitis in certain groups." (PMID 31801640, 2019). "The inflammasomes affect the pathological process of viral hepatitis through its downstream secretion of inflammatory cytokines interleukin-1β (IL-1β) and IL-18 or induction of pyroptosis resulting from cleaved gasdermin D (GSDMD)." (PMID 38817443, 2024). "Thus, IL-18–mediated cytotoxic activity appears to be a common contributing factor to liver injury in viral hepatitis, and the genetic variations in IL-18/IL-18BP likely may have a significant impact on host susceptibility and/or the severity of the disease." (PMID 34066709, 2021). "Nevertheless, the majority of eligible studies only focused on associations between polymorphisms in CTLA-4/IL-18 and viral hepatitis, so we could not explore genetic-environmental interactions in this meta-analysis." (PMID 31801640, 2019). "During the acute phases of viral hepatitis, particularly HAV, massive secretion in patients' serum of IL-18 and IL-15 has been observed." (PMID 31507607, 2019). "IL-18BP (Binding Protein) is also involved and blocks IL-18 action and seems critical as a means of limiting deleterious hepatic NK responses in hepatic aggression models (see Acetaminophen-Induced ALF and Post-Viral Hepatitis A ALF)." (PMID 31507607, 2019).
viral myocarditis (4 papers, 2019 to 2023). Myocarditis that is caused by an infection with a viral agent. "However, there are some controversial studies; for example, the expression of IL-18RNA in the myocardium of patients with dilated cardiomyopathy is downregulated, and IL-18 has been shown to play a beneficial role in viral myocarditis caused by the cerebrocarditis virus." (PMID 37047468, 2023). "For instance, IL-18 reduces the severity of viral myocarditis by inducing the cardiac expression of IFN-γ mRNA and increasing the activity of natural killer cells in the spleen." (PMID 37047468, 2023). "In the current study, we found that NLRP3 inflammasome was highly expressed in viral myocarditis with increased levels of IL-18 and IL-1β." (PMID 36418383, 2022). "In CVB3-induced viral myocarditis, IL-37 treatment obviously weakened the upregulation of NLRP3 inflammasomes (NLRP3, ASC, and caspase-1), and the activation of NLRP3 inflammasomes as evidenced by decreased inflammatory mediators (IL-1β and IL-18)." (PMID 36418383, 2022).